ZGLP1 (zinc finger GATA like protein 1)
Description:
Transcriptional regulator that plays a key role in germ cell development. Determines the oogenic fate by activating key genes for the oogenic program and meiotic prophase entry. Acts downstream of bone morphogenetic protein (BMP) by regulating expression of genes required for the oogenic programs, which are repressed by Polycomb activities in sexually uncommitted germ cells. Regulates expression of STRA8, a central downstream effector for the meiotic program. Acts independently of retinoic acid (RA). In males, not required for germ-cell sex determination, but required to allow the spermatogonia to efficiently accomplish the meiotic prophase.
Synonyms: GLP-1; GLP1; GATAD3
Tractability: No criterion of Open Targets' tractability assessment is met for any kind of drug.
Gene: Protein-coding gene on chromosome 19 (10,304,803 to 10,309,880, reverse strand). Ensembl gene ENSG00000220201.
Subcellular location: Nucleus
Subcellular location (Human Protein Atlas): Nucleoplasm; Vesicles
Gene Ontology:
Molecular function: DNA-binding transcription factor activity, RNA polymerase II-specific; sequence-specific DNA binding; zinc ion binding
Biological process: negative regulation of transcription by RNA polymerase II; oocyte development; positive regulation of transcription by RNA polymerase II; regulation of transcription by RNA polymerase II; spermatogenesis; regulation of DNA-templated transcription
Cellular component: nucleus; nucleoplasm
Genetic constraint (gnomAD): Loss-of-function variants: 12 observed, 21.65 expected, observed/expected ratio (o/e) 0.55, 90% interval 0.35 to 0.9. The upper end of that interval is the gene's LOEUF score, 0.9, which puts it in group 3 of 6, group 1 being the genes least tolerant of losing a copy. Missense variants: 295 observed, 316.91 expected, observed/expected ratio (o/e) 0.93, 90% interval 0.85 to 1.02. Synonymous variants: 148 observed, 135.2 expected, observed/expected ratio (o/e) 1.09, 90% interval 0.96 to 1.25.
Homologues: Orthologues: macaque ZGLP1 (94% identical), chimpanzee ZGLP1 (86% identical), pig ZGLP1 (63% identical), rat Zglp1 (58% identical), mouse Zglp1 (57% identical), guinea pig ZGLP1 (53% identical), dog ZGLP1 (46% identical), zebrafish zglp1 (26% identical), Drosophila melanogaster GATAd (15% identical), Drosophila melanogaster srp (12% identical), Caenorhabditis elegans elt-2 (8% identical), Caenorhabditis elegans elt-4 (5% identical). Paralogues in human: TRPS1 (18% identical), GATA2 (15% identical), GATA3 (14% identical), GATA6 (14% identical), GATA1 (12% identical), GATA4 (12% identical), GATA5 (11% identical).
Diseases named in the same sentence as ZGLP1 in open-access papers:
ZGLP1 is named in the same sentence as 1 disease in open-access papers, as found by Europe PMC text mining. Sharing a sentence is not in itself a finding about the gene and the disease.
ZGLP1 shares sentences with these, for which no sentence is quoted: COVID-19 (1 paper).